ALB (albumin)
Diseases named in the same sentence as ALB in open-access papers (continued):
Sharing a sentence is not in itself a finding about the gene and the disease.
Hypertension (continued). "First, the intensity of fibrinogen deposition positively correlated with eGFR, serum albumin, and the levels of hemoglobin, but negatively correlated with age, the levels of serum fibrinogen, serum C4, and the ratios of patients with hypertension." (PMID 36787086, 2023). "Female sex, age, history of hypertension, red blood cell count, albumin, urea, and uric acid (UA) were independently correlated with CKD." (PMID 37828481, 2023). "The Cox-proportional hazard regression model included female gender, age, albumin levels, smoking status, hypertension, osteoporosis and history of cancer within predictors of mortality over the follow-up period." (PMID 37198577, 2023). "Twenty-eight out of 160 (18%) patients had elevated urine albumin, (micro) albuminuria or proteinuria; eleven of whom were diagnosed with hypertension and sixteen with DM2." (PMID 37547314, 2023). "In our study, we adjusted for age, sex, BMI, hypertension, arterial plaque, thyroid disease, jaundice, albumin, globulin, total bile acid, total bilirubin, ALP, GGT, HDLC, LDLC, total cholesterol, triglycerides, and APTT." (PMID 37978445, 2023). "Ileus, underweight, DM, and hypertension also exhibited indirect effects through various pathways involving albumin, hemoglobin, and heart failure." (PMID 38831863, 2023). "Second, the causal relationships of DM, hypertension, heart failure, GERD, peptic ulcer disease, ileus, underweight, albumin, and hemoglobin on all-cause mortality were confirmed by SEM analysis." (PMID 38831863, 2023). "Multiple logistic analysis showed that comorbidities (cancer, chronic-kidney disease and hypertension) were also independent variables influencing mortality in aged over 85 years patients, besides ABNP-associated factors (albumin, BUN, NLR and pulse)." (PMID 37528213, 2023). "Fasting glucose, triglycerides, creatinine, albumin-to-creatinine ratio and uric acid levels were also higher among patients with hypertension, whereas HDL-cholesterol and estimated glomerular filtration rate (eGFR) were lower." (PMID 38173815, 2023). "Age, sex, BMI, alcohol consumption, hypertension, dyslipidemia, hemoglobin, albumin, hemoglobin A1c, triglyceride, uric acid and creatinine were significantly associated with KSD in univariable analysis." (PMID 37340386, 2023). "The present study revealed that PBC patients with hypertension tended to be older, had lower levels of serum ALB, and higher rates of cirrhosis, T2DM, and mortality." (PMID 38027142, 2023). "Patients who received human albumin as adjunctive therapy were more likely to be concomitant with hypertension, heart failure and coronary heart disease (p < 0.05)." (PMID 37089426, 2023). "IDO activity was found to be associated with chronic kidney disease (CKD)-related indicators, such as calcium, phosphorus, uric acid, hemoglobin, albumin, coagulation indicators, and hypertension." (PMID 37509627, 2023). "In summary, we found that DM, hypertension, heart failure, GERD, peptic ulcer disease, ileus, underweight, lower circulating albumin and hemoglobin levels were associated with all-cause mortality in patients with chronic schizophrenia." (PMID 38831863, 2023). "Nine variables were selected based on their statistical significance: Gender, Age, Stroke, Carotid Atherosclerosis, Hypertension, Creatinine, Lipoprotein(a), Albumin to Globulin Ratio, and Homocysteine." (PMID 38259650, 2023). "Through LASSO regression, we selected 12 indicators: Gender, Age, Stroke, Carotid Atherosclerosis, Hypertension, Creatinine, Total Cholesterol, Low-Density Lipoprotein, Lipoprotein(a), Albumin to Globulin Ratio, Homocysteine, and Monocyte-to-HDL Ratio." (PMID 38259650, 2023). "We also found associations between all-cause mortality with DM, hypertension, heart failure, GERD, peptic ulcer disease, ileus, underweight, fasting glucose, triglycerides, albumin, and hemoglobin in our study cohort." (PMID 38831863, 2023).
Hypertension (continued). "The increases in these novel RAS pathway parameters were correlated with a reduction in urinary albumin excretion in patients with T2D and hypertension." (PMID 36899369, 2023). "In the fully adjusted model, stroke risks for age, race, education level, smoking, hypertension, SCr and serum albumin levels (ln transform) remained strongly correlated." (PMID 37682189, 2023). "HRs for each1SD increase of URR and Kt/V by subgroups, including those of age, sex, DM, CHF, hypertension, hemoglobin, albumin, and BW, were all analyzed and compared." (PMID 37264037, 2023). "Several acknowledged risk factors for incident HF in DM include older age, longer duration of DM, cumulative glycemic burden, higher BMI, atherosclerotic disease, elevated urinary albumin concentration, impaired renal function and hypertension." (PMID 37985994, 2023). "Alternatively, when hypertension was included as an independent variable in the models and systolic BP and ARB/ACEi use were excluded, LRG1 level was still associated with urinary albumin excretion." (PMID 37916147, 2023). "Subgroup analysis of the interactions of renal function progression event with age, sex, hypertension, level of baseline kidney function and baseline albumin using Cox proportional hazard model." (PMID 35707542, 2022). "Upon multivariate analysis, a low value of albumin level was found to be an independent risk factor for ACS (odds ratio [OR]: 0.16 [0.057–0.454], p = 0.001) after adjusting for age, hypertension, family history of CVD and fibrinogen." (PMID 35881574, 2022). "The following variables were extracted: age, sex, eGFR (estimated glomerular filtration rate), ACR (urinary albumin-to-creatinine ratio), presence of type 2 diabetes, hypertension and heart failure." (PMID 35701727, 2022). "The semi-laboratory analyses of this study showed that ALB levels were important influencing features of hypertension." (PMID 36225955, 2022). "The highest urinary albumin excretion was found in patients with hypertension, especially in patients with hypertension and COPD." (PMID 36579215, 2022). "The most common treatment- and laboratory-related AEs were hypertension (46.2%) and decreased albumin (53.8%), respectively." (PMID 36505818, 2022). "In the follow-up EDIC-study, the beneficial effects on albumin excretion and the reduced incidence of hypertension after the DCCT suggested that previous intensive treatment had extended benefit in delaying progression of diabetic nephropathy." (PMID 35201418, 2022). "A urine albumin/creatinine ratio (UACR) <30 mg/g is considered to be normal, while increased risk of incident hypertension and cardiovascular disease mortality in subjects with high normal UACR level had been observed." (PMID 35721762, 2022). "On univariate analyses, several factors including sudden onset, hypertension, liver cirrhosis, Child-Pugh grade, hemoglobin (Hb), TB, serum albumin (ALB), AFP, hepatitis B virus surface antigen (HBsAg), and tumor size were potential predictors of STRHCC." (PMID 35155255, 2022). "The univariate predictors of RIS were age, history of hypertension, serum creatinine, lymphocyte count, platelet count, albumin level, stroke etiology, and neurological deterioration." (PMID 35405949, 2022). "The univariate analysis showed that hypertension, macroscopic hematuria, more severe microscopic hematuria, BUN, hemoglobin, uric acid, eGFR, 24 h urinary protein, T1–T2, TA-serum albumin, and TA-hematuria were significantly associated with poorer prognosis." (PMID 36431262, 2022). "There were significant differences between the two groups regarding age, neutrophil count, lymphocyte count, BUN, serum albumin and congestive heart failure, renal dysfunction, hypertension and CHD." (PMID 36522751, 2022). "On the other hand, others found an increased incidence of pre-eclampsia and hypertension in women with low serum albumin." (PMID 36474218, 2022).
Hypertension (continued). "The sex, chest radiograph, gout, hypertension, Hb, ALB, and RBP were significantly different between the two groups." (PMID 36510169, 2022). "After confounding variables were adjusted, like age, sex, ALB, ALT, TBA, creatinine, hypertension, and dyslipidemia, the association between high-level Lp(a) and carotid plaques in participants with DM remained significant." (PMID 36465632, 2022). "The types of AEs that occurred in both groups were hypertension, appetite loss, fatigue, proteinuria, hypothyroidism, hand or foot skin reaction, AST/ALT elevation, and a worse modified albumin–bilirubin (mALBI) grade." (PMID 35600400, 2022). "With regard to comorbidities, 38.5% were taking medication for hypertension, and 60.0% had low albumin." (PMID 33999142, 2022). "A significantly higher prevalence of hypertension, cardiac disease, and serum reactive C-protein and lower albumin values in AKI-CKD patients was recorded." (PMID 35258071, 2022). "After adjustment for confounders, age, sex, BMI, smoking, DBP, past history of hypertension, past history of DM, past history of dyslipidemia, serum albumin and CKD were still significantly related to cataracts." (PMID 36568781, 2022). "Before matching, the TIR < 70% group had a higher WBCs count, higher neutrophil counts, higher blood glucose at admission, lower rates of hypertension, lower rates of kidney disease, and lower albumin levels." (PMID 35962366, 2022). "Pairwise analysis revealed a statistical difference between urinary albumin levels in patients with hypertension (Group I), hypertension and COPD (Group II), and patients with COPD (Group III)." (PMID 36579215, 2022). "Differences in the characteristics and prevalence of hypertension, decreased estimated glomerular filtration rate (eGFR), and increased albumin-to-creatinine ratio (ACR) were compared between clusters." (PMID 36072936, 2022). "We found that NIHSS, ASPECTS, history of hyperlipidemia, history of hypertension, neutrophil count, monocyte count, lymphocyte count, albumin level, and MLR were different between the two groups." (PMID 36247122, 2022). "The results of univariate regression analyses found albumin, fibrinogen, family history of CVD, age, hypertension all to be significant risk factors for CVD." (PMID 35881574, 2022). "Proximal tubules took up albumin and accumulated excessive albumin in luminal protein casts (arrows), suggesting that overloading of the albumin uptake machinery occurs in hypertension." (PMID 35835746, 2022). "The most essential CKD features are packed red blood cell count, albumin, cell volume, serum creatinine, specific gravity, hemoglobin, and hypertension." (PMID 35054287, 2022). "In contrast, PS, vital capacity, hypertension, size of tumor, and albumin level were detected differences." (PMID 36004276, 2022). "Venular calibre widening depended on age, hypertension history, mean arterial pressure, albumin levels and arteriolar calibre, but again the only independent determinant of venular calibre appeared to be arteriolar calibre." (PMID 35918491, 2022). "Improved hemoptysis, dyspnea, hypertension, gingival and vaginal bleeding.Amelioration of anemia, thrombocytopenia and serum albumin.Decreased immune cell infiltration and DAH." (PMID 36465325, 2022). "The combination of PAPP-A levels in the first trimester, albumin levels, eGFR, and total bilirubin levels just before delivery was optimal for predicting the severity of pregnancy-related hypertensive disorders." (PMID 36140589, 2022). "In conclusion, maternal albumin levels before delivery and placental syncytial knot status are closely related to disease severity in women with pregnancy-related hypertensive disorders." (PMID 36140589, 2022). "In univariate analyses, the following factors were associated with an increased risk of development of HCC: male sex, old age, higher BMI, AST, ALT, GGT, FIB-4 and APRI, lower platelet count, HbA1c, and albumin, and the presence of hypertension." (PMID 33427937, 2021).
Hypertension (continued). "A higher level of initial hematuria was an independent risk factor for relapse (adjusted HR, 1.43; 95% CI, 1.15–1.78) in Model C after adjustment for age, sex, hypertension, serum albumin, eGFR, proteinuria, and use of RAAS blockers and IS agents." (PMID 34957132, 2021). "The patients with sarcopenia were older and more likely to have a higher prevalence of hypertension and a lower level of preoperative albumin." (PMID 34199110, 2021). "Higher age, urine albumin and comorbid illness including hypertension, dyslipidemia, and obesity were observed in our study." (PMID 34174842, 2021). "In these patients, increases in plasma sPRR parallel urine albumin/creatinine ratio, hypertension, and decline in renal function." (PMID 33933156, 2021). "The last model contained nine predictors: surgery, age, albumin, sex, serum creatinine, malignancy, hypertension, ability to live independently, and cardiovascular and cerebrovascular diseases." (PMID 34838076, 2021). "Higher levels of white blood cells, neutrophils, creatinine, uric acid, and phosphorus were observed in the morning hypertension group, whereas the levels of lymphocytes, total protein, albumin, and calcium were lower in this group." (PMID 34513954, 2021). "The logistic regression model for the development of CI-AKI, using the parameters of DKK3/creatinine, albumin/creatinine, eGFR and age and hypertension, provided an AUC of 0.75 (95% CI 0.71–0.79)." (PMID 33275197, 2021). "Logistic regression including DKK3/creatinine, albumin/creatinine, eGFR, age and hypertension computed an AUC of 0.74 (95% CI 0.69–0.78)." (PMID 33275197, 2021). "Others such as preoperative hemoglobin, albumin, WBC count, hypertension, CKD, and emergency surgery have been identified as risk factors for morbidity and mortality after colorectal surgery in general." (PMID 34159014, 2021). "Male sex, presence of hypertension, lower HbA1c and albumin, and higher GGT and FIB-4 were significant predictors of HCC development in diabetic patients." (PMID 33427937, 2021). "She presented at 7 years of age with kidney dysfunction in the form of SRNS, with accompanying oedema, ascites, pleural effusions, hypertension, proteinuria (7.5 g/day), a serum creatine level of 0.8 mg/dL and a serum albumin of 20 g/L." (PMID 32631816, 2021). "Multivariate logistic regression analyses showed that the FIB-4 index was an outstanding predictor of HCC development along with male sex, presence of hypertension, lower HbA1c and albumin levels, and higher BMI and gamma-glutamyl transpeptidase levels." (PMID 33427937, 2021). "The univariate analysis showed that BMI, hypertension, TLNs, ratio of PLNs, PLNs, albumin level, and age correlated with the DDASD (P < 0.05)." (PMID 33510284, 2021). "They found that participants with higher urinary albumin excretion at baseline were more likely to develop hypertension (OR 1.18; per 1-unit In (UAE) change; 95% CI 1.03–1.36) after a mean 4.2 year of follow-up." (PMID 33712668, 2021). "In univariable logistic regression analysis, DM, hypertension, heart failure, serum albumin <4.0 mg/dL, BUN/Cr ratio >15, and hyperuricemia were associated with early initiation of dialysis." (PMID 34219598, 2021). "After adjusting sex, age, hypertension, proteinuria, serum ALB, high Scr, TC, and TG, the same result was shown; the presence of renal TLOs remains independently associated with positive anti-PLA-2R autoantibody (OR = 2.27, 95% CI: 1.17–4.43)." (PMID 35211487, 2021). "The most common adverse events were decreased albumin (55.0%), hypertension (48.3%) and decreased platelet count (46.7%) in the TACE + lenvatinib group." (PMID 33877527, 2021). "Of these, hypertension, massive proteinuria, renal impairment, albumin, and severe histological findings have been widely accepted." (PMID 35005032, 2021).
Hypertension (continued). "Although the use of the urine albumin-to-creatinine ratio is recommended in evaluating renal damage in all patients with hypertension, the urine dipstick test also has high sensitivity and specificity in screening for proteinuria." (PMID 34640330, 2021). "The most common AEs of all grade in the TACE + lenvatinib group were decreased albumin (55.0%), hypertension (48.3%) and decreased platelet count (46.7%)." (PMID 33877527, 2021). "Multivariable adjusted for age, sex, DM, hypertension, coronary artery disease, cerebrovascular disease, BMI, fasting glucose, albumin, hemoglobin, triglyceride, total cholesterol, HDL-cholesterol, LDL-cholesterol, calcium–phosphate product, ABI and baPWV." (PMID 34945724, 2021). "By univariate analysis, age, hypertension, neutrophils, lymphocytes and platelets counts, alanine aminotransferase, aspartate aminotransferase, albumin, urea, calcium, phosphorus, bicarbonate, APTT, PT, d-dime, CRP, PCT, and LDH, were associated with AKI." (PMID 34541999, 2021). "The study found out that BMI, serum albumin level, hypertension, TLNs, and ratio of PLNs were independent predictors of drainage duration in patients undergoing MRM." (PMID 33510284, 2021). "Multivariable was adjusted for age, sex, DM, hypertension, coronary artery disease, cerebrovascular disease, BMI, fasting glucose, albumin, hemoglobin, triglyceride, total cholesterol, HDL-cholesterol, LDL-cholesterol, calcium–phosphate product, ABI and baPWV." (PMID 34945724, 2021). "At the time of biopsy 16.3% of the patients had stage 1, 8.2% stage 2 hypertension, and the rest were normotensive, 22.4% of children had an eGFR < 90 ml/min/1.73 m2 and 63% low serum albumin levels (< 35 g/L)." (PMID 33089378, 2021). "In this study, IDO was also found to be associated with other CKD-related indicators, such as calcium, phosphorus, uric acid, hemoglobin, albumin, coagulation indicators, and hypertension." (PMID 33506062, 2021). "Compared to the eGFR trajectory T0 group, the T1 group had higher serum albumin levels, and the T2 group had more elderly people, but the T3 group had a greater likelihood of hypertension." (PMID 34912823, 2021). "By combining clinical symptoms—e.g., hypertension, low serum albumin, lymphopenia, elevated high-sensitivity C-reactive protein (hsC-RP)—and temporal CT scans, deep learning models were shown to outperform the human-based COVID-19 diagnosis." (PMID 34420513, 2021). "Patients with hypertension, coagulopathy, liver cirrhosis, or obesity were more likely to be given the albumin group." (PMID 34916544, 2021). "Seven predictors were selected: obesity, cardiovascular conditions distinct from high blood pressure, albumin, natremia, ferritin, CK and LDH." (PMID 33956870, 2021). "Patients with poor outcomes were older; more likely to have a history of hypertension, coronary artery disease, and valvular heart disease; and had higher blood glucose and plasma d-dimer and lower albumin levels at admission." (PMID 33505348, 2020). "Excessive urinary albumin excretion following exercise has been reported in patients with metabolic syndrome, including patients with hypertension and type 2 diabetes." (PMID 32539802, 2020). "In this study, we demonstrated that an increased serum adiponectin level was significantly associated with old age, female sex, hypertension, higher serum creatinine level, higher UACR, lower BMI, reduced eGFR, and lower serum albumin level." (PMID 32221363, 2020). "Injury to the kidney manifests as increased BUN, decreased total protein and albumin in the circulation, systemic hypertension, glomerulosclerosis, fibrosis, and hemosiderin deposition in the renal tissue." (PMID 33336158, 2020). "On the other hand, a urinary albumin/creatinine ratio of less than 30 mg/g is a predictor of hypertension and cardiovascular mortality." (PMID 32606332, 2020).